CCDC172 (coiled-coil domain containing 172)
Synonyms: C10orf96; MGC35062
Tractability: No criterion of Open Targets' tractability assessment is met for any kind of drug.
Gene: Protein-coding gene on chromosome 10 (116,324,388 to 116,380,029, forward strand). Ensembl gene ENSG00000182645.
Subcellular location: Cytoplasm; Cell projection, cilium
Gene Ontology:
Molecular function: protein binding
Cellular component: cytoplasm; sperm midpiece; cilium
Genetic constraint (gnomAD): Loss-of-function variants: 6 observed, 7.56 expected, observed/expected ratio (o/e) 0.79, 90% interval 0.43 to 1.54. That is too few expected variants to judge how well the gene tolerates losing a copy. Missense variants: 83 observed, 81.72 expected, observed/expected ratio (o/e) 1.02, 90% interval 0.85 to 1.22. Synonymous variants: 25 observed, 27.78 expected, observed/expected ratio (o/e) 0.9, 90% interval 0.65 to 1.26.
Homologues: Orthologues: chimpanzee CCDC172 (99% identical), macaque CCDC172 (96% identical), pig CCDC172 (83% identical), dog CCDC172 (83% identical), rabbit CCDC172 (83% identical), guinea pig CCDC172 (78% identical), mouse Ccdc172 (70% identical), rat Ccdc172 (70% identical), tropical clawed frog ccdc172 (48% identical), zebrafish ccdc172 (31% identical).